RN7SL42P (RNA, 7SL, cytoplasmic 42, pseudogene)
Gene: Miscellaneous RNA gene on chromosome 11 (59,214,406 to 59,214,699, reverse strand). Ensembl gene ENSG00000263999.
Homologues: Orthologues: macaque Metazoa_SRP (95% identical). Paralogues in human: RN7SL1 (83% identical), RN7SL2 (83% identical), RN7SL296P (82% identical), RN7SL408P (82% identical), RN7SL3 (81% identical), RN7SL336P (81% identical), RN7SL126P (81% identical), RN7SL679P (81% identical), RN7SL44P (80% identical), RN7SL14P (80% identical), RN7SL220P (80% identical), RN7SL357P (80% identical), and 701 more.